PIK3CA (phosphatidylinositol-4,5-bisphosphate 3-kinase catalytic subunit alpha)
Diseases named in the same sentence as PIK3CA in open-access papers (continued):
Sharing a sentence is not in itself a finding about the gene and the disease.
cancer (continued). "We found that most top cancer-related mutations: EGFR and PIK3CA, were shared across matched adenomatous and squamous pathologies in all four samples." (PMID 37051524, 2023). "We found 141 patients (11.8%) with a PIK3CA and/or PIK3R1 mutation across 20 different cancer types." (PMID 36934165, 2023). "In this study we identified mutations in three known human mutation hotspots PIK3CA p.H1047R, PIK3CA p.E545D and KRAS p.G12V/D, which have all previously been shown to be implicated in human breast neoplasia and even other types of carcinomas in humans." (PMID 36635367, 2023). "Focusing on confirmed carcinomas (n = 11) we found four genes which were mutated in more than one sample: PIK3CA, KRAS, ZZEF1 and DOCK10 were each mutated in two of the carcinomas (18% each)." (PMID 36635367, 2023). "PI3K-AKT, an important cell signaling cascade, can be physiologically triggered in carcinomas by either genetic alteration of PIK3CA and Protein kinase B (AKT1) or cognitive debilitation of phosphatase and tensin homolog deleted on chromosome 10 (PTEN)." (PMID 37102943, 2023). "The PI3K/Akt pathway plays an important role in the tumorigenesis of thyroid cancer, and two of the genes we identified in the poorly differentiated carcinoma component, PIK3CA and PIK3CB, belong to this pathway." (PMID 37249797, 2023). "Similar observations have also been made in other cancers: in an in vitro model of therapy resistant ovarian cancer, Thakur and Ray found that NF-κB activates TNFα and PIK3CA via a feedback loop leading to the maintenance of stem cell-like characteristics." (PMID 35780223, 2022). "We conclude that the PIK3CA public NeoAg is typically clonal, immunogenic in patients with cancer and, in select cases, correlated with a mechanism of neoepitope-specific immune resistance." (PMID 35484264, 2022). "BRAF/PIK3CA double mutant cancers had higher rates of chromosomal stability than BRAF mutant cancers with wild type PIK3CA." (PMID 36079062, 2022). "We found that ECs harbored not only known mutations in driver genes, such as ARID1A, CTNNB1, PIK3CA, and PTEN, but also novel mutations in cancer-related genes, such as KMT2C and PRKAR1A." (PMID 35626111, 2022). "USP13 is localized adjacent to PIK3CA in the 3q26.3 locus, which is frequently amplified in human cancers such as brain, lung, ovarian, esophageal and cervical cancers, and high USP13 expression is correlated with poor survival outcomes." (PMID 36385557, 2022). "Responses to alpelisib were not significantly different when analyzing only BC PDX; however, when considering pan-cancer PDX we observed significantly better responses in tumors with PIK3CA-mut/gain compared to PIK3CA-mut/neut (p = 0.023)." (PMID 35181669, 2022). "Several studies have addressed the role of the PIK3CA pathway in cervical cancer and other types of HPV-associated cancers." (PMID 35267596, 2022). "Mutations in cancer-related genes (KMT2C, NOTCH2, PRKAR1A, SDHA, and USP6) and genes related to EC (ARID1A, CTNNB1, PIK3CA, and PTEN) were identified with high frequencies among the three samples." (PMID 35626111, 2022). "in cancer cells, activating mutations in PIK3CA and AKT1 genes, major players of PI3K-AKT-mTOR signalling pathway, are widely reported in many cancers and present attractive targets for the identification of new therapeutics and better cancer management." (PMID 35317488, 2022). "Circulating T cells specific for the PIK3CA public NeoAg were detected in ~30% of HLA-A*03:01+/Mut PIK3CA+ patients with cancer." (PMID 35484264, 2022).
cancer (continued). "Studies have shown that PIK3CA and HRAS are prone to a mutation in a variety of tumors, resulting in their persistent hyperactivity, which promotes cancer cell proliferation and migration." (PMID 35794555, 2022). "Efforts to target new hotspot mutations in PIK3CA were on the rise, which induced PI3K-based cancer drugs continuing to emerge in the clinical trials." (PMID 35242279, 2022). "The phase I trial CBYL719X2101 (NCT01219699) included 134 heavily pre-treated patients with PIK3CA alterations across advanced cancer types and demonstrated sensitivity to the single agent alpelisib." (PMID 35565291, 2022). "On the other hand, the subset of EGFR signaling in cancer was clearly over-represented in patients three and four, both showing mutated KRAS, and PIK3CA was also affected in the oldest patient (patient four)." (PMID 36005154, 2022). "Disturbances in the PI3K/Akt/mTOR pathway play a central role in cancer, the most common deregulations being a loss of PTEN, amplification of the PIK3CA or AKT gene locus and PIK3CA mutations." (PMID 35780223, 2022). "The expression of PIK3CA was significantly different among different stages in cancers UCEC, KIRC, OV, LIHC, SKCM, MESO, and UCS." (PMID 35242279, 2022). "Chromosome 3q25-26 is a frequently amplified locus in HNSCC that harbors multiple cancer-associated genes including WWTR1 (TAZ), PIK3CA, and SOX2." (PMID 35456049, 2022). "mTOR/AKT is activated in numerous cancers, generally through mutations in upstream regulators, including PTEN and PIK3CA." (PMID 35884604, 2022). "PIK3CA mutations, as well as AKT activation by phosphorylation (pAKT), are detected in many cancers, especially in BC." (PMID 37082114, 2022). "TFs associated with PIK3CA mutations were involved in WNT signaling, epithelial–mesenchymal transition, and cancer stem cell transition, including ELF3, TFEC, STAT4, STAT5B, NFATC1, GLIS1, CDC5L and AR." (PMID 36243974, 2022).
cancer (continued). "More than half of these mutations were common cancer driver mutations, including canonical mutations in KRAS and PIK3CA." (PMID 36311816, 2022). "The gene encoding for the catalytic sub-unit alpha of PI3K kinase, PIK3CA, is the most frequently mutated oncogene in ER-positive/HER2-negative/luminal cancers in all three cohorts and is significantly enriched in tumors with high mutation counts." (PMID 35329928, 2022). "Overall, PI3K isoform-specific inhibitors have demonstrated high rates of stable disease in PIK3CA-altered cancers and are better tolerated than pan-PI3K and dual PI3K/mTOR inhibitors." (PMID 35887235, 2022). "Compared with BRAF mutant/PIK3CA wild type cancers, double mutant cancers were even more often MSI or POLE positive." (PMID 36079062, 2022). "We demonstrated the capability of these assay to establish that PIK3CA-H1047R confers three cancer hallmarks on MCF10A cells: sustained proliferation, resistance to apoptosis and enhanced migratory and invasive capacities." (PMID 36471068, 2022). "Together, these data indicate that the PIK3CA public NeoAg is immunogenic and capable of driving T cell clonal expansion in vivo in a subset of cancer patients." (PMID 35484264, 2022). "Ipatasertib (GDC-0068) is also effective both in cancer cell lines and in xenograft models with activation of Akt due to complete loss of PTEN (PTEN-null), decreased expression of PTEN or mutations in PIK3CA." (PMID 36180910, 2022). "Among these patients, about one third or 3.4% of the whole cohort had BRAF and PIK3CA double mutant cancers." (PMID 36079062, 2022). "MYC, CCNE1, TERT, KRAS and genes from the PI3K/AKT/mTOR pathway (e.g. PIK3CA) are amongst the commonest amplified cancer genes in HGSOC2,9–13." (PMID 36289203, 2022). "Other activating factors of PAM pathway, including PIK3CA mutation, AKT1 mutation, AKT2 amplification, and loss of cancer suppressor gene PTEN, can also cause resistance to anti‐HER2 agents, such as trastuzumab and lapatinib." (PMID 38089455, 2022). "MYC alterations have been found in cancer but were mutually exclusive with PIK3CA, PTEN, APC, or BRAF alterations, suggesting that MYC is a distinct oncogenic driver." (PMID 35328644, 2022).
cancer (continued). "i3 cancers had more frequent KRAS, PIK3CA and BRAF mutations, including mutations known to be associated with more prominent MAPK pathway upregulation." (PMID 35773407, 2022). "As the next step, KNTC1 knockdown caused some cancer-associated factors P-Akt, CCND1, c-Myc, CDK1 and PIK3CA depletion." (PMID 35933405, 2022). "On the other hand, such kind of inhibition induced by eL31 depletion led to the downregulation of cancer-associated elements P-Akt, CCND1, CDK6 and PIK3CA." (PMID 36309731, 2022). "PI3K/ATK/mTOR and Ras/MAPK pathway activation are involved with constitutive PD-L1 regulation in many cancers; loss of PTEN or mutations in PIK3CA lead to PI3K/ATK/mTOR pathway activation, while mutations in EGFR or Ras lead to Ras/MAPK pathway activation." (PMID 35164673, 2022). "The same group of authors showed that somatic mutations of PIK3CA were detected in 17 (40%) tumors, and the majority (71%) of these were ARID1A-deficient carcinomas." (PMID 35457244, 2022). "Accordingly, mutations in the gene encoding p110α (PIK3CA) and the phosphatase enzyme PTEN which dephosphorylates PIP3 back to PIP2 are found in many cancers." (PMID 33503847, 2021). "In human cancers, including OCCC, three hotspot mutations in PIK3CA have been identified: E542K, E545K, and H1047R." (PMID 34172890, 2021). "Overexpression of this locus is also a common trait in cancers of the lung, esophagus, cervix and especially ovary, with almost 50% of tumors showing high PIK3CA levels (COSMIC database)." (PMID 34062774, 2021). "Several cancer-associated genes—Fibroblast Growth Factor Receptor-3 (FGFR3), phosphatidylinositol-4,5-bisphosphate 3-kinase catalytic subunit alpha (PIK3CA) and N-ras proto-oncogene (NRAS) are identified as mutant in HT1197 when compared to HT137642." (PMID 33790357, 2021). "For instance, PIK3CA, KRAS and BRAF harbored 1457, 805 and 707 driver mutations from pan-cancer cohorts, respectively." (PMID 33179738, 2021). "As such, it will be of interest to investigate the prevalence of mosaic PIK3CA variants in DGC and other cancers diagnosed in young adults." (PMID 34075207, 2021). "Overall, 34 specimens harbored driver mutations in five cancer genes (EGFR, PIK3CA, KRAS, CTNNB1, and MET), which are canonical driver mutations." (PMID 33407425, 2021). "PIK3CA mutations in different domains such as adaptor-binding domain (ABD), C2 domain, and kinase domains have been frequently detected in different cancer types." (PMID 34493320, 2021).
cancer (continued). "AZD5363, a pan-AKT inhibitor, was reported to improve progression-free survival in advanced cancers with AKT1 mutations However, the number of patients with MAC is too small to draw a conclusion on the pattern of AKT1, PIK3CA, TGFβ mutation." (PMID 33738258, 2021). "The four genes selected through our process which are dysregulated along with CLDN1 and CLDN7 (PIK3CA, SLC6A6, ASAP1, and TMEM-43) are implicated in a variety of cancers." (PMID 34571860, 2021). "In summary, we show that the high expression of FSCN1 indicates poor prognosis and radiotherapy response of cancer patients with PIK3CA alterations." (PMID 34249689, 2021). "The PI3K/AKT/mTOR pathway is thought to play a fundamental oncogenic role in cancers and is activated by the activating events in oncogenes PIK3CA, AKT1/2, and MTOR, or inactivating events in tumor suppressor genes such as PTEN, INPP4B, etc72." (PMID 34448553, 2021). "Rlip depletion has been shown to inhibit PIK3CA in other cancers, and both Rlip and PIK3CA are known to regulate CDE." (PMID 34944997, 2021). "Several studies have reported the role of PIK3CA alterations in resistance to cancer therapy, including TKI treatment." (PMID 34249687, 2021). "While a relatively limited number of known oncogenes (e.g., RAS, MYC, PIK3CA, EGFR, BCR-ABL) seem to underlie a large percentage of cancers, a variety of new genes have emerged as low-frequency cancer drivers." (PMID 34504101, 2021). "Copy number amplification events in CCND1, CCND3, CDK6, ERBB2, FGFR1, MET, and PIK3CA also showed higher expression compared to wild types across various cancer types." (PMID 34429404, 2021). "These included the following genes known for their association with cancer: BRAF (V600E) and PIK3CA (E545K), both harboring hotspot mutations and three other possible driver genes, SDHC (H127R), DDR2 (R668C), and FANCD2 (C1130Y)." (PMID 34301805, 2021). "We detected three frequently (>5%) altered genes (ATM, ERBB2 and PIK3CA) for which targeted therapies are available in other cancer types." (PMID 34771420, 2021). "PIK3CA is one of the most frequently mutated genes along with ARID1A in OCCC, and co-mutation of Pik3ca and Arid1a in mouse ovaries causes cancer similar to human OCCC." (PMID 34172890, 2021). "Proof-of-concept responses were observed in patients with PIK3CA-mutant cancers treated with AZD5363." (PMID 34298731, 2021). "A considerable fraction (approximately 10 ~ 30%) of cancer patients carry abnormally activated PIK3CA mutants." (PMID 33827485, 2021). "Two groups have independently identified different subsets of cancer cell lines that are highly sensitive to OGDH knockdown, including those harboring PIK3CA mutations." (PMID 34827664, 2021). "DNA mismatch repair process-related genes, such as MLH1, and well-known CRC driver genes, such as PIK3CA, were included in the common gene set, suggesting their important functions in the generation of these cancer cells." (PMID 34507604, 2021). "Several cancer-associated genes, such as KRAS and PIK3CA, are frequently mutated in the endometriotic epithelium." (PMID 34202354, 2021). "PIK3CA-related cancers and PROS share almost the same PIK3CA mutational profile, with about 80% of mutations occurring at three hotspots, E542, E545, and H1047." (PMID 34568242, 2021).